LINC00880 (long independently transcribed non-coding RNA 880)
Gene: Long non-coding RNA gene on chromosome 3 (157,074,061 to 157,128,595, reverse strand). Ensembl gene ENSG00000243629.
Diseases named in the same sentence as LINC00880 in open-access papers:
LINC00880 is named in the same sentence as 7 diseases in open-access papers, as found by Europe PMC text mining. Sharing a sentence is not in itself a finding about the gene and the disease. The quoted sentences say what the papers report.
glioblastoma (1 paper, 2023). The most malignant astrocytic tumor (WHO grade IV). "The TCGA pan-cancer analysis revealed upregulated LINC00880 expression across most types of cancers, including head and neck squamous cell carcinoma (HNSC), liver hepatocellular carcinoma (LIHC), kidney renal clear cell carcinoma (KIRC), glioblastoma (GBM), and LUAD." (PMID 37620336, 2023).
head and neck cancer (1 paper, 2024). A primary or metastatic malignant neoplasm affecting the head and neck. "Further, LINC00880 was overexpressed in head and neck cancer." (PMID 39329063, 2024).
testicular cancer (1 paper, 2023). A primary or metastatic malignant neoplasm that affects the testis. "GTEx database analysis showed that among normal human tissues, the expression of LINC00880 was the highest in the testis, and previous research had demonstrated that the sequence encoding LINC00880 was located at a genome-susceptible region (3q25.31) in testicular cancer." (PMID 37620336, 2023).
cancer (2 papers, 2023 to 2024). A tumor composed of atypical neoplastic, often pleomorphic cells that invade other tissues. "LINC00880 knockdown represses cancer cell proliferation, colony formation, migration, and in vivo tumor formation." (PMID 39329063, 2024).
tumor (2 papers, 2023 to 2024). "We previously characterized SE-associated lncRNAs (SE-lncRNAs) in LUAD specimens using a SE-lncRNAs microarray, among which, LINC00880 attracted our attention due to its markedly upregulated expression in tumor samples." (PMID 37620336, 2023). "Additionally, we also constructed lung metastasis model, and the analysis of lung metastatic colonies showed that LINC00880 drastically promoted tumor metastasis." (PMID 37620336, 2023). "Results of the qRT-PCR also validated that the LINC00880 was strongly expressed in tumor than the matched normal tissue, as well as in LUAD tumor cells when compared to the normal lung cell." (PMID 37620336, 2023).
LINC00880 also shares sentences with these, for which no sentence is quoted: head and neck squamous cell carcinoma (1 paper); hepatocellular carcinoma (1).